CXCR4 (C-X-C motif chemokine receptor 4)
Diseases named in the same sentence as CXCR4 in open-access papers (continued):
Sharing a sentence is not in itself a finding about the gene and the disease.
tumor (continued). "Amongst lung, pancreatic and ileal NETs, increased levels of CXCR4 seem to correlate with higher tumor malignancy and are associated with poor patient outcomes." (PMID 28186979, 2017). "In HCC, CXCR4 staining of the tumor vessels was significantly associated with poor patient outcomes." (PMID 29282035, 2017). "Tumor cell-associated expression of CXCR4 was present in 9 samples, whereas ETA expression was observed in 3 cases only." (PMID 29163802, 2017). "CXCR4 positivity in tumor samples at initial diagnosis were associated with reduced overall survival, in particular with respect to increasing T/N status, local and systemic recurrency." (PMID 29348861, 2017). "The binding of SDF-1 to CXCR4 induces αvβ6 integrin and upregulates certain tumor-associated proteases including urokinase plasminogen activator and metalloproteinase 9 to promote cancer invasion." (PMID 28196146, 2017). "The exposure of the cell-surface CXCR4 is a hallmark of a small distinctive cancer stem cell (CSC) that displays tumor formation, invasion, and migration capabilities accompanied with an innate resistance to chemotherapy." (PMID 28196146, 2017). "CXCR4 is implicated in tumor cell motility, survival, and growth and is often overexpressed in SCLC tumors and SCLC cell lines." (PMID 28299514, 2017). "The CXCR4 chemokine receptor is expressed in a variety of cancers and has been linked to proliferation, invasion, and metastasis in many tumor cells, thus CXCR4 has been suggested as an important therapeutic target for inhibiting cancer metastasis." (PMID 28534824, 2017). "We therefore propose that imaging of CXCR4 with [68Ga]Pentixafor is a potential diagnostic tool for tumours close to or within the CNS and suggest this being studied in clinical trials." (PMID 28577295, 2017). "In the other subgroup of 22 IGHV mutated cases, with a stronger BCR/CXCR4 downregulation profile, a majority (64%) had tumor progression with lymphadenopathy, and 7 of them required treatment for nodal progression with a median follow up of 9.2 years." (PMID 27127886, 2016). "Local SDF-1α and its receptor CXCR4, which is expressed on tumor-associated MDSCs, participate in the recruitment of MDSCs to the tumor environment." (PMID 27996037, 2016). "In the present study, we further emphasized the BCR-dependent down-regulation of CXCR4 that was linked to tumor burden in both IGHV mutated and unmutated patients." (PMID 27127886, 2016). "The chemokine CXCL12 (C-X-C chemokine ligand 12) and its ligand CXCR4 (C-X-C chemokine receptor type 4) are involved in the development of several organs, including the kidney, and are also associated with tumor growth and metastasis." (PMID 27830498, 2016). "Due to its overexpression in a variety of tumor types, the chemokine receptor 4 (CXCR4) represents a highly relevant diagnostic and therapeutic target in nuclear oncology." (PMID 27655427, 2016). "Reduced tumor cell proliferation and survival seems to be associated with CXCR4-based inhibition of microenvironmental support." (PMID 27835905, 2016). "We propose that NF-κB dependent tumor-associated inflammation co-participate in malignant progression concomitant to normal hematopoietic failure through disruption of CXCL12/CXCR4 and VLA4/VCAM-1 communication axes." (PMID 27594840, 2016). "The same mechanisms, which maintained HSC quiescence, are also implicated in tumour cell dormancy (CXCR4, CXCL12 and angiopoietin-1)." (PMID 27782035, 2016). "Low-CXCR4 expressing GL26-Cit-sh2CXCR4 cells have diminished association with blood vessels compared to CXCR4-sufficient GL26-Cit-NT implanted tumor." (PMID 27863376, 2016). "Related to its role in angiogenesis, chemotaxis, and cell proliferation, CXCL12/CXCR4 signaling has also been linked to different pathologies including tumor progression and metastasis, as discussed in more detail later." (PMID 26347749, 2015).
tumor (continued). "Activation of molecular pathways such as p38 mitogen-activated protein kinase (p38 MAPK) induces tumor progression and is associated with CXCR4 expression." (PMID 26318034, 2015). "CXCR4 induced tube formation and morphological changes including cell polarization and extension of invadopodia associated with tumor progression." (PMID 26318034, 2015). "siRNA mediated CXCR4 knock-down resulted in inhibition of tumor cell migration and was associated with reduced expression of pAKTS473 and pPRAS40T246 proteins (P<0." (PMID 25775124, 2015). "Among chemokines implicated in this cascade; SDF-1α/CXCR4 regulates organ specific colonization of metastatic tumor cells." (PMID 26231656, 2015). "CXCR4 overexpression on the cell membrane is, however, the key parameter for successful CXCR4-directed tumor targeting in vivo, both for diagnostic imaging and in particular for endoradiotherapeutic approaches." (PMID 25736399, 2015). "Previous studies has shown that binding of SDF-1α to CXCR4 plays a role in tumour metastasis by increasing invasion associated with MMP-9 and MMP-2 activation 20,27,28." (PMID 25753200, 2015). "It has been suggested that CXCR4 expression in primary tumor is associated with a higher risk for bone metastasis." (PMID 26161302, 2015). "In cancer, high CXCR4 expression is frequently associated with tumor dissemination and poor prognosis." (PMID 25736399, 2015). "Song and colleagues reported that TIMP-1 activates carcinoma-associated fibroblasts and suppresses tumor apoptosis via SDF-1/CXCR4 signaling, which promotes HCC progression." (PMID 26549110, 2015). "The expression level of CXCR4 dynamically changes depending on the change of the tumor environment caused by tumor development or metastasis." (PMID 26083776, 2015). "To investigate the mechanism behind the spontaneous aggregation of fibroblast-like cells and LAM cells we examined the role of the CXCR4 / CXCL12 axis which is responsible for the recruitment of cancer associated fibroblasts in tumours." (PMID 25978616, 2015). "Many studies have found an association between the CXCR4 expression level and fast tumor recurrence as well as poor patient outcomes." (PMID 25671300, 2015). "CXCR4 antagonist-expressing oncolytic virotherapy decreased tumor growth in murine EOC, and was associated with reduced accumulation of myeloid cells and Tregs." (PMID 25888637, 2015). "The stromal derived factor-1 (SDF-1)/CXCR4 axis is associated with tumour aggressiveness and metastasis in PCa." (PMID 25444175, 2015). "This suggests that CXCR4 is progressively expressed as malignant disease becomes more advanced, thus there appears to be a direct association with tumor progression and metastasis." (PMID 26318034, 2015). "High expression of CXCR4 has been associated with invasion and migration of tumour cells in patients with BC, a role confirmed both in vivo and in vitro." (PMID 25358600, 2014). "Inhere we investigated the role of DGKα in invasive signaling of SDF-1α, one of the key signals driving metastasis, whose receptor, CXCR4, is strongly associated to tumor growth and spontaneous metastasis formation." (PMID 24887021, 2014). "Addition of the CXCR4 antagonist AMD3100 to sorafenib in an HCC mouse model prevented the increase in tumor-associated fibrosis and significantly inhibited HCC growth compared to sorafenib alone." (PMID 24646914, 2014). "In different tumor types, expression of the C-X-C chemokine receptor type 4 (CXCR4) has been associated with tumor dissemination and poor prognosis." (PMID 24912495, 2014). "Tumor metastases into areas rich in SDF-1 are associated with the expression of CXCR4 on the surface of cancer cells and their uptake to SDF-1-rich sites along a concentration gradient." (PMID 24416254, 2014).
tumor (continued). "Our data support this notion, as CTCE-9908-treated tumors showed enhanced necrotic areas, suggesting that loss of the CXCL12/CXCR4 axis mediated cell survival leading to enhanced necrosis in tumor cells." (PMID 24472670, 2014). "In OS patients, overall disease-free and metastasis-free survival was found to be inversely related to the expression of CXCR4-encoding mRNA in primary tumor tissue." (PMID 24390633, 2014). "Recently, it was shown that the CXCL12/CXCR4 pathway is involved in tumor-associated fibrosis by increasing myofibroblast infiltration and differentiation." (PMID 24646914, 2014). "Tumor progression, especially tumor metastasis, is also affected by CXCR4-SDF-1 signaling through the induction of tumor-associated integrin activation and signaling." (PMID 24618817, 2014). "Other chemokine receptors implicated in Treg trafficking to tumor sites include CXCR4, which drives Treg cells toward tumor site via interactions with CXCL12 that is produced within the tumor microenvironment, as well as CCR8 and CCR10 (86, –88)." (PMID 23874336, 2013). "Soluble PC1CP can induce the expression of VEGF and CXCR4 in a β1 integrin-dependent manner, and this has been linked to chondrogenic tumor vascularization and progression." (PMID 24490159, 2013). "SDF1a and CXCR4 have been implicated in angiogenesis—in particular with the processes that facilitate the progression of cancer, such as tumour cell proliferation, metastasis and angiogenesis." (PMID 23422038, 2013). "In the current study, CXCR4 expression levels in tumor cells were positively associated with primary tumor invasion and clinical stage progression." (PMID 23497377, 2013). "Over-expression of CXCR4 induces tumor metastasis through enhanced proliferation of cells caused by stimulating the MAP/Erk kinase pathway and through accelerating vascularization by activating vascular endothelial growth factor (VEGF)." (PMID 25285238, 2013). "We conclude that, in BCs, Nef-M1, through interaction with CXCR4, inhibits primary tumor growth and metastasis by causing apoptosis." (PMID 25285238, 2013). "The CXCR4 chemokine receptor has been implicated in many malignancies, and the SDF-1α/CXCR4 axis has been shown to be involved in several aspects of tumor progression, including angiogenesis, metastasis and survival." (PMID 24094005, 2013). "It is well established that the CXCR4/SDF-1 pathway is implicated in the recruitment of MSCs to sites of injury as well as to areas of tumor development." (PMID 24069395, 2013). "Tumor associated fibroblast (TAF) secreted CXCL-12 (SDF-1) was found to directly promote the growth of CXCR4 expressing tumors in vivo and in vitro." (PMID 23744479, 2013). "Flow cytometric analysis after incubation of the tumor cell suspensions with MSAP-Ac-TZ14011 underlined that CXCR4 positivity increased during the progression of MIN-O lesions." (PMID 23326303, 2013). "This analysis revealed that higher CXCR4 expression and cytoplasmic localization of CXCR4 were significantly associated with the lymph node status of the tumor." (PMID 23181100, 2012). "SDF1/CXCR4 is the signaling pathway most implicated in regulating recruitment and migration of BMDCs in tumor models." (PMID 22675549, 2012). "The chemokine CXCL12 and its cognate receptor, CXCR4, have been implicated in numerous tumour types where expression promotes tumour growth, angiogenesis, metastasis and suppresses tumour immunity." (PMID 22415233, 2012). "Organs such as the liver or lung produce SDF-1 and thereby increase the risk of developing metastasis by attracting circulating tumour cells expressing CXCR4." (PMID 22433494, 2012). "Intracellular expression of CR (in particular nuclear expression of CXCR4) assessed at primary tissue level has been associated to the metastatic destination of tumor cells and to patient outcome in several different cancer entities." (PMID 22433180, 2012).
tumor (continued). "Recently, CXCR4 expression was associated with advanced tumor stage and the development and recurrence of lymphatic or distant colorectal liver metastases (CRLM)." (PMID 21349176, 2011). "CXCR4 is the most frequently over-expressed chemokine receptor on tumor cells, especially on cancer stem cells, and is associated with metastasis to distant organs and/or aggressive disease in breast cancer, glioblastoma, and pancreatic cancer." (PMID 24212934, 2011). "Tumours with high expression of CXCR4 are associated with more aggressive phenotypes showing increased rates of distant metastases and poorer clinical outcome." (PMID 20492653, 2010). "Vascular CXCR4 expression was significantly associated with higher local tumour extent as well as higher UICC-stages." (PMID 20386750, 2010). "In the prent study, CXCR4 was found to be present in both cytoplasm and nucleus of tumor cells, and cytoplasmic expression was associated with lymph node metastasis." (PMID 20181250, 2010). "When correlating CXCR4 expression in tumour cells with various clinicopathological parameters, CXCR4 expression was significantly associated with higher local tumour extent (T-status; p = 0.030)." (PMID 20386750, 2010). "They found that low oxygen concentration induced high expression of SDF1α and CXCR4, in different cell types (monocytes, monocyte-derived macrophages, tumour-associated macrophages, endothelial cells, and cancer cells)." (PMID 20492653, 2010). "The chemokine receptor CXCR4 has been implicated in the mechanism underlying tumor cell metastasis to bone." (PMID 19508713, 2009). "In our study, CXCR4 tumour overexpression was associated with a higher risk of LN metastasis, liver recurrence and was found to be an independent negative prognosis factor for OS but not for DFS." (PMID 19352387, 2009). "Stromal cell-derived factor-1α and CXCR4 expression were significantly associated with LN metastasis, tumour stage, and survival of CRC patients." (PMID 18443596, 2008). "Theexpression of the chemokine receptor CXCR4 has been reported in various epithelial, mesenchymal, and hematopoietic tumors.In several entities, its expression was linked to tumor dissemination and poorprognosis." (PMID 19266088, 2008). "In different tumor entities, the level of chemokine receptor CXCR4 expression has been linked with tumor progression and decreased survival." (PMID 19266088, 2008). "In other tumour entities, expression of the chemokine receptor CXCR4 has been linked to tumour dissemination and poor prognosis." (PMID 16819541, 2006). "The expression of the chemokine receptor CXCR4 has been shown to play key mechanisms in migration and metastasis with associated tumor progression and poor prognosis in a limited number of malignancies." (PMID 17176471, 2006). "High CXCR4 expression was associated with tumour dissemination in colorectal, breast and oral squamous cell carcinoma." (PMID 16819541, 2006). "In our patients, a strong CXCR4 expression was significantly associated with locally progressed tumours, lymph node and distant metastases." (PMID 16819541, 2006). "In different tumour entities, expression of the chemokine receptor 4 (CXCR4) has been linked to tumour dissemination and poor prognosis." (PMID 16819541, 2006). "The observed association between strong CXCR4 expression and poor tumor-specific survival suggests that CXCR4 expression levels influence the metastatic behavior of NPC." (PMID 15978137, 2005). "Functionally, CXCR4 not only recruits immunosuppressive cells, such as neutrophils, tumor-associated macrophages, but also engages with transcription factors to activate the NF-κB pathway, collectively reshaping the TME to promote immune evasion and metastatic dissemination." (PMID 40607416, 2025). "Additionally, ETV4 regulates the expression of cytokines and cytokine receptors such as CCL2 and CXCR4, promoting tumor-associated macrophages (TAMs) and MDSCs recruitment and fostering an immunosuppressive microenvironment." (PMID 41502516, 2025).
tumor (continued). "Elevated levels of CXCL12 and/or CXCR4 in the blood have been associated with higher tumor grades and may indicate resistance to treatment, making it a candidate for monitoring therapeutic efficacy." (PMID 40134607, 2025). "Therapeutic strategies targeting the neuroimmune axis show promise, including β-blockers combined with PD-1 inhibitors to reverse T cell exhaustion, CXCR4 antagonists disrupting nerve- tumor-associated macrophage (TAM) crosstalk, and radiofrequency ablation of perirenal nerve plexus." (PMID 41142779, 2025). "Additionally, CXCR4 has been implicated in OS cell migration and invasion, facilitating tumor metastasis to distant sites." (PMID 41024311, 2025). "The CXCL12/CXCR4 axis is specifically implicated in tumor progression." (PMID 40433410, 2025). "CXCR4, a G protein‐coupled receptor, is associated with tumor growth, metastasis, and survival." (PMID 39575761, 2025). "This may be explainable by the upregulation of EZH2 in SMARCB1-deficient tumours, which enhances CXCR4 expression through the repression of the tumour-suppressive microRNAs miR-622 and miR-9." (PMID 40422882, 2025). "High expression of CXCR4 is also associated with increased TAM infiltration in tumor tissues." (PMID 40890855, 2025). "The selective expression of CXCR4 on tumor-associated vessels in higher-grade OSCC suggests that CXCR4 may serve as a potential vascular biomarker, reflecting tumor progression and angiogenic activity." (PMID 41210695, 2025). "Moreover, it regulates gene expression linked to tumor invasiveness, metastasis, and angiogenesis, such as C-X-C motif chemokine receptor 4 (CXCR4), VEGF, and MMPs." (PMID 40420174, 2025). "The binding of PMN-MDSCs in state 1 to CXCR3 was associated with cell recruitment and immune modulation in the early tumour microenvironment, whereas in other states, the involvement of CXCR4 was linked to cell migration, survival, and other immune evasion mechanisms." (PMID 40429821, 2025). "Therefore, the diagnostic use of [68Ga]Ga‐CXCR4 PET/CT will probably be limited to tumours with high CXCR4 expression." (PMID 40923371, 2025). "While strong cytomembranous expression of CXCR4 correlates with worse prognosis, other studies have reported that nuclear staining of CXCR4 in tumor cells may be linked to improved clinical outcomes." (PMID 41149503, 2025). "Similarly, in tumor-stage MF, high CXCR4 expression is seen in malignant CD3-deficient T cells, whereas only a small fraction of CD3+ inflammatory T cells express the receptor." (PMID 40861461, 2025). "Furthermore, the expression of CXCR4 by cancer cells seems to be associated with malignancy potential and tumor recurrence." (PMID 39457017, 2024). "CXCR4 radiolabeling in the CB, in juxtaposition to the tumor, might serve as a surrogate marker indicating an association with patient survival." (PMID 39085419, 2024). "Besides, CXCR4 has been reported to be overexpressed in numerous malignancies and is associated with tumor growth, invasion, angiogenesis, metastasis, recurrence, and drug resistance." (PMID 38561388, 2024). "CXCR4+ CD8+ T cells exit tumors through CXCL12+ tumor-associated lymphatic vessels." (PMID 38786066, 2024). "CXCR4 and its ligands have been linked to tumor immunity, cancer development, and metastasis." (PMID 39350256, 2024). "This phenomenon may be caused by the interaction among of anti-CXCR4 peptide and overexpressed CXCR4 in tumor." (PMID 38982161, 2024). "Replication of in vivo stimuli is crucial for potential applications of these 3D CLL models (e.g., drug testing) as, for example, CXCR4-mediated interactions hold cancer cells within a protective tumor microenvironment and are linked to resistance to therapeutic agents." (PMID 39655330, 2024). "Other receptor molecules like sLex and CXCR4 are implicated in tumor immune evasion mechanisms." (PMID 38181281, 2024). "TNBC tumor growth and metastasis are implicated in the CXCR4/SDF-1 axis, which may be targeted as a therapeutic target." (PMID 39070795, 2024).